RNU7-176P (RNA, U7 small nuclear 176 pseudogene)
Gene: Small nuclear RNA gene on chromosome 2 (10,815,485 to 10,815,546, reverse strand). Ensembl gene ENSG00000238962.
Homologues: Orthologues: macaque U7 (97% identical), pig U7 (77% identical). Paralogues in human: RNU7-124P (84% identical), RNU7-57P (82% identical), RNU7-6P (82% identical), RNU7-1 (81% identical), RNU7-13P (81% identical), RNU7-2P (81% identical), RNU7-35P (81% identical), RNU7-41P (81% identical), RNU7-52P (81% identical), RNU7-59P (81% identical), RNU7-60P (81% identical), RNU7-9P (81% identical), and 141 more.